BRCA1 (BRCA1 DNA repair associated)
Diseases named in the same sentence as BRCA1 in open-access papers (continued):
Sharing a sentence is not in itself a finding about the gene and the disease.
clear cell carcinomas (10 papers, 2016 to 2023). "Whereas BRCA1 mutation variant (p.L63*) is rather sensitive to platinum treatment, clear cell carcinomas are highly resistant to chemotherapy." (PMID 33922533, 2021). "Conversely, only a small fraction of clear cell carcinomas harbored BRCA1 or 2 mutations (8% for both BRCA1 and BRCA2)." (PMID 31771620, 2019). "Although the major histological subtype of BRCA1/2-associated tumors was HGSC (22/27 cases, 81.5%), pathogenic germline BRCA1/2 variants were also found in patients with other subtypes including endometrioid and clear cell carcinomas." (PMID 29348823, 2017). "Here, we were unable to identify pathogenic BRCA1/2 mutations in patients with endometrioid or clear cell carcinomas." (PMID 27907908, 2016).
endometrioid carcinoma (10 papers, 2015 to 2025). "Two patients with OC (HGSC and endometrioid carcinoma, respectively) carried both BRCA1 and BRCA2 mutations simultaneously." (PMID 37064128, 2023). "Four types of pathogenic mutations in BRCA1 (Ser454Ter, Gln541Ter, Arg1751Ter, and Gln1779AsnfsTer14) were detected in 8 unrelated patients (7.9%) belonging to serous and endometrioid carcinoma groups." (PMID 32856862, 2020). "Tier IA variants were found in BRCA1 and BRCA2 genes from three ovarian high grade serous carcinomas and one uterine endometrioid adenocarcinoma, respectively." (PMID 36010253, 2022). "Most PVs had a high-grade serous (HGS) histology except one BRCA1 with grade 3 endometrioid carcinoma and one BRIP1 with mixed epithelial adenocarcinoma." (PMID 34503154, 2021). "We excluded from our analyses, low-grade endometrioid adenocarcinomas, mucinous cancers and mixed cell carcinomas lacking serous components, as these are least likely to harbour germline BRCA1/BRCA2 mutations." (PMID 25884701, 2015).
invasive carcinoma (10 papers, 2007 to 2025). A carcinoma that is not confined to the epithelium, and has spread to the surrounding stroma. "Pathogenic BRCA1/2 variants correlated with younger onset age, higher frequencies of bilateral and triple-negative BC (TNBC), invasive carcinomas, high histological grades, and family history of BC and other cancers." (PMID 33461583, 2021). "We used immunohistochemistry to examine the expression of the hypoxia markers HIF-1α, CAIX and Glut-1 in DCIS and available invasive carcinoma lesions of 32 BRCA1, 16 BRCA2 and 77 non-BRCA mutation-related cases." (PMID 23409121, 2013). "Preliminary microarray comparisons on DCIS and invasive carcinoma samples dissected from formalin-fixed paraffin sections showed a consistent downregulation of two previously identified FHIT-related genes, caspase 1 and BRCA1 in lesions underexpressing FHIT." (PMID 17164758, 2007).
renal cell carcinoma (10 papers, 2017 to 2025). "Here, we report a case of renal cell carcinoma in patient with concurrent germline mutations in BRCA1 and RAD51 genes." (PMID 38512353, 2024). "None of the BRCA1/2 mutations in the renal cell carcinoma cases included in this study were deleterious (0/14)." (PMID 33054725, 2020).
small cell lung carcinoma (10 papers, 2015 to 2024). Small cell lung cancer (SCLC) is a highly aggressive malignant neoplasm, accounting for 10-15% of lung cancer cases, characterized byrapid growth, and early metastasis. "Our findings indicate that the BRCA1 and MYC/MYCN-RAD51 axes govern the response of small cell lung cancer to BI-2536 and its combination with alisertib." (PMID 39085197, 2024). "Notably, we observed elevated somatic BRCA1/2 rates in several non-BRCA-associated lineages such as uterine sarcoma (7.3%), small cell lung cancer (2.6%), and bladder (1.7%) compared to those in BRCA-associated lineages." (PMID 36418296, 2022). "Moreover, PARP inhibition itself induces HR deficiency by reducing the expression of the E2F1 target genes involved in DNA replication and cell cycle regulation (e.g., PCNA, MCM7, and CCNA2) and HR factors such as BRCA1/2 and RAD51, as shown in prostate and small cell lung cancer." (PMID 32029455, 2020).
soft tissue sarcoma (10 papers, 2016 to 2024). A malignant neoplasm arising from muscle tissue, adipose tissue, blood vessels, fibrous tissue, or other supportive tissues excluding the bones. "Univariate Cox proportional hazards regression analysis for survival in various subgroups of soft-tissue sarcomas according to the expression of BRCA1, BRCA2, PARP1, and γH2AX." (PMID 27643881, 2016). "High PARP-1 expression alone and in combination with the expression of other DNA repair molecules (γH2AX, BRCA1, and BRCA2) is prognostic factor for shorter survival in soft tissue sarcoma patients." (PMID 33572586, 2021). "In this study, we evaluated the immunohistochemical expression of PARP1, γH2AX, BRCA1, and BRCA2 and their prognostic significance in 112 cases of soft tissue sarcoma (STS)." (PMID 27643881, 2016). "The expression status of PARP1, γH2AX, BRCA1, and BRCA2 according to the histological type of soft-tissue sarcoma." (PMID 27643881, 2016). "Kaplan-Meier survival analysis with Log-rank test according to the expressions of PARP1, γH2AX, BRCA1, and BRCA2 in various histological types of soft-tissue sarcomas." (PMID 27643881, 2016). "The correlation between the clinicopathological variables and the expression of PARP1, γH2AX, BRCA1, and BRCA2 in soft tissue sarcomas." (PMID 27643881, 2016).
carcinosarcoma (9 papers, 2013 to 2024). A malignant tumor composed of a mixture of carcinomatous and sarcomatous elements. "Given the patient’s young age (48 year-old) and the close relation between carcinosarcoma and a minor HGSC component in the ovary, BRCA1/2 mutation was tested." (PMID 36199118, 2022). "However, rearrangement signature analysis on the three carcinosarcoma models did not detect BRCA1/2-associated signatures." (PMID 35012638, 2022). "The association of BRCA1 mutations with other histotypes, commonly grouped under the term of metaplastic breast carcinomas (MBC) and including squamous, adenosquamous and tumors with biphasic morphology carcinomas (so-called carcinosarcomas), was also described." (PMID 23374397, 2013).
endometrioid ovarian cancer (9 papers, 2008 to 2025). "This mutation was also the most common mutation found in our previous study of 74 women with serous and endometrioid ovarian cancers screened for specific BRCA1/BRCA2 mutations." (PMID 25884701, 2015). "We could demonstrate that rupatadine can effectively inhibit in vitro cell proliferation and migration of clear cell, serous, BRCA1 mutant, and endometrioid ovarian cancer cells." (PMID 34571986, 2021).
esophageal squamous cell carcinoma (9 papers, 2013 to 2024). Esophageal squamous cell carcinoma (ESCC) is a type of esophageal carcinoma (EC) that can affect any part of the esophagus, but is usually located in the upper or middle third. "In esophageal squamous cell carcinoma, the BRCA1_rs799917 T>C SNP inhibits mir-638–mediated regulation of BRCA1, thus reducing BRCA1 expression and increasing cancer cell proliferation." (PMID 36922933, 2022). "In addition, BRCA1 protein and mRNA expression varies from high to low levels in human esophagus squamous cell carcinoma." (PMID 27410681, 2016). "Quantitative real-time polymerase chain reaction (qPCR) was performed to examine BRCA1 mRNA expressions in paraffin-embedded specimens from 144 patients with advanced or metastatic esophageal squamous cell carcinoma who received cisplatin- or docetaxel-based first-line treatments." (PMID 23326344, 2013). "In human esophageal SCC, the protein expression of p16, RAR-β2, and TIMP3 is decreased, and ERCC1 and BRCA1 protein expression varies." (PMID 27410681, 2016). "The synergistic effects of JWA, XRCC1 and BRCA1 mRNA expression on personalized therapy remain unknown in advanced esophageal squamous cell carcinoma (ESCC)." (PMID 25925371, 2015).
metastatic carcinoma (9 papers, 2014 to 2024). A carcinoma which has spread from the original site of growth to another anatomic site. "Enrolling patients with tumors harboring pathogenic mutation genes other than ATM, BRCA1 and BRCA2 was challenging owing to the low prevalence of pathogenic alterations affecting these genes in patients with metastatic cancer (<1%)." (PMID 37277454, 2023). "Although we describe patients with aggressive metastatic cancer, the presence of low levels of BRCA1 protein had a worse prognosis even in early-stage CRC." (PMID 35280729, 2022). "We identify inactivation of BRCA1, BRCA2, RAD51C, and PALB2 as the most frequent genetic cause of HRD pan-cancer in both primary and metastatic cancer, with the latter two genes resulting in the same mutational footprints as BRCA2 (consistent with the findings of recent studies in breast cancer)." (PMID 33149131, 2020). "The first clinical trial focused on the use of Olaparib, and included patients with positive pathogenic BRCA1/2 mutations, Her2 negative, locally advanced, or metastatic cancer that have been previously treated by chemotherapy (OlympiAD)." (PMID 32823908, 2020). "MDA-MB-231 is a triple receptor negative metastatic carcinoma cell line that expresses wild type BRCA1." (PMID 25460500, 2014). "Furthermore, the results of this test confirmed also that the putative factors responsible for the malignant transformation of the BRCA1-KO fibroblasts were exclusively present in the serum of patients with metastatic cancer and were absent in the serum of healthy patients." (PMID 27179759, 2016).
mucinous carcinoma (9 papers, 2006 to 2023). "PVs in BRCA1/2 and established non‐BRCA1/2 OC predisposition genes were found across all tumor phenotypes, except mucinous carcinoma." (PMID 37345881, 2023). "As BRCA1/2-mutated CRC tumors are more frequently of the mucinous adenocarcinoma subtype compared to BRCA1/2 wild-type tumors, this finding further suggests a role for the loss of BRCA1 activity in the development of mucinous adenocarcinoma." (PMID 34611475, 2021). "Other trends included higher frequency of advanced lymph node stage and mucinous adenocarcinoma among BRCA1 mRNA-low CRC and higher frequency of males in BRCA1 mRNA-high BC and CRC." (PMID 34611475, 2021). "Our novel observations include correlation between BRCA1 mRNA-high tumor expression and age <45 years at CRC diagnosis, BRCA1 mRNA-low expression and basal BC, mucinous adenocarcinoma among BRCA1 mRNA-low CRC, and higher frequency of males in BRCA1 mRNA-high BC and CRC." (PMID 34611475, 2021).
serous ovarian tumors (9 papers, 2009 to 2024). "HRD, which is not limited to BRCA1/2 mutations, is present in approximately 50% of high-grade serous ovarian tumors." (PMID 39077473, 2024). "In conclusion, the application of a targeted assay using next‐generation sequencing of FFPE samples allowed the identification both somatic and germline BRCA1/2 mutations in a group of patients with serous ovarian tumors." (PMID 27167707, 2016). "However, similar to studies in TNBC, we found that average AR expression was higher in BRCA1 and BRCA2-mutated high-grade serous ovarian tumors compared to non-mutated BRCA tumors." (PMID 34926721, 2019).
breast adenocarcinoma (8 papers, 2009 to 2023). "BRCA1 was overexpressed in intraductal cribriform breast adenocarcinoma patients in the TCGA database, with a fold change of 3.454 and a p value of 1.92 × 10−6." (PMID 35409110, 2022). "HBOC is due to mutations in the BRCA1 and BRCA2 genes; it is characterized by ductal or lobular breast adenocarcinoma and epithelial ovarian carcinoma." (PMID 24625245, 2014). "HBOC is due to mutations in the BRCA1 and BRCA2 genes and is characterized by breast adenocarcinoma and/or epithelial ovarian carcinoma." (PMID 24625245, 2014). "Similarly, mice with mammary gland-specific deletion of full-length Brca1 but retention of Brca1-Δ11 develop mammary adenocarcinomas characterised by genetic instability." (PMID 19904273, 2009).
cystic fibrosis (8 papers, 2011 to 2024). Autosomal recessive disorder caused by pathogenic variants in the CFTR gene (cystic fibrosis transmembrane conductance regulator), which encodes a chloride and bicarbonate channel expressed in epithelial cells, and follow the diagnosis criteria. "The same approach has been adopted by several companies for the detection of SNPs in multiple genes such as BRCA1 and cystic fibrosis genes." (PMID 35629095, 2022).
familial hypercholesterolemia (8 papers, 2012 to 2025). An inheritable form of hyperlipidemia, in which there are excess lipids in the blood. "It has been suggested for several diseases that extreme PGS risk confers a similar magnitude of increased risk as the presence of Mendelian pathogenic variants (for example, familial hypercholesterolemia for coronary artery disease, and BRCA1 or BRCA2 for breast cancer)." (PMID 39966645, 2025). "Combining a microfluidic amplification system with massive parallel sequencing is an effective method for mutation scanning, which has previously been employed for the diagnostics of familial hypercholesterolemia and here was applied to BRCA1 and BRCA2 sequencing." (PMID 23110154, 2012). "In this context, our laboratory workflow is able to analyze BRCA1/2, CFTR, and familiar hypercholesterolemia genes in the same 454 Junior run." (PMID 25922769, 2015).
hereditary tumor syndromes (8 papers, 2019 to 2026). "In this study, in addition to two novel SNVs, BRCA1 p.Y809H (3/49) and BRCA2 p.Y57*(1/49), a known pathologic SNV of BRCA2 (c.3396delA, p.K1132Nfs) (Hereditary cancer-predisposing syndrome) was also identified in 44.91% (22/49) of GIST tumors." (PMID 34805171, 2021). "Therefore, offering a NGS-based multi-gene panel testing to all BBC patients may significantly increase the detection rates of germline PVs in other cancer susceptibility genes beyond BRCA1/2, avoiding underestimation of the number of individuals affected by a hereditary tumor syndrome." (PMID 32854451, 2020).
lobular carcinomas (8 papers, 2011 to 2021). "BRCA1 N/C ratio was significantly higher in mixed ductal and lobular carcinoma than other histological subtypes (p<0.0001) when BRCA1 was quantified using dual IF method." (PMID 28863181, 2017). "In the Mexican population, five pathogenic variants (9.4%) were found in women with invasive ductal and lobular carcinomas, younger than 36 years of age and BRCA1/2 negative." (PMID 32888145, 2021).
medulloblastoma (8 papers, 2015 to 2025). A malignant, invasive embryonal neoplasm arising from the cerebellum. "A pathogenic variant in BRCA1 was also noted and was the only BRCA-associated medulloblastoma in our cohort." (PMID 39184053, 2024). "Notably, V66-exatecan demonstrated the ability to cross the BBB, effectively targeting BRCA1- and BRCA2-deficient autochthonous medulloblastomas." (PMID 41077566, 2025). "The genetic aberrations in the two patients with a history of medulloblastoma were one patient with BRCA1-splice site 4987-1 G>A, which corresponds to the splice acceptor site near to C-terminus and a second patient with two different alterations in the PTCH-1 gene, N97fs*43 and K163fs*6." (PMID 25859559, 2015). "Our patient with medulloblastoma was found to have BRCA1-splice site 4987-1-G>A that may lead to production of a truncated protein that prevents the BRCT domain from binding to several tumor suppressor proteins." (PMID 25859559, 2015). "To confirm the genetic interactions between BRCA1 and PALB2 in redox regulation and cell fitness in human cells, we took advantage of our recently generated PALB2 knockout DAOY medulloblastoma cells and the same cells reconstituted with a human PALB2 cDNA." (PMID 33893322, 2021).
microcephaly (8 papers, 2014 to 2021). A congenital or acquired developmental disorder in which the circumference of the head is smaller than normal for the person's age and sex. "Among them, two groups of excitatory neurons, THEMIS-PLA2G7 and FEZF2-SCN7A, express several PSGs involved in DNA damage response and mutated in patients with microcephaly such as BRCA1, NHEJ1, RNF168, and TOP3A." (PMID 33441416, 2021). "Among those, a number of DNA damage response genes associated with microcephaly in humans such as BRCA1, NHEJ1, TOP3A, and RNF168 show strong signs of positive selection and might have played a role in human brain size expansion during primate evolution." (PMID 33441416, 2021). "How BRCA1 mutations cause microcephaly in humans remains largely unknown." (PMID 33441416, 2021). "Several other DNA damage response proteins, which are binding partners of BRCA1 (such as SLX4, TOP3A, RNF168, and MCPH1) are also associated with microcephaly." (PMID 33441416, 2021). "Therefore, a high incidence of microcephaly caused by the lack of NBS1 or BRCA1 suggests that in addition to the unrepaired-DSB-mediated apoptosis pathway, other pathways are involved in the development of microcephaly." (PMID 27367050, 2016). "Furthermore, mice lacking the breast cancer gene Brca1 were also reported to show severe microcephaly." (PMID 27367050, 2016).